FAM90A27P (family with sequence similarity 90 member A27, pseudogene)
Gene: Protein-coding gene on chromosome 19 (53,277,462 to 53,284,947, forward strand). Ensembl gene ENSG00000189348.
Subcellular location (Human Protein Atlas): Cytosol
Homologues: Paralogues in human: FAM90A13 (29% identical), FAM90A14 (29% identical), FAM90A15 (29% identical), FAM90A23 (29% identical), FAM90A24 (29% identical), FAM90A10 (29% identical), FAM90A16 (29% identical), FAM90A17 (29% identical), FAM90A22 (29% identical), FAM90A5 (29% identical), FAM90A1 (29% identical), FAM90A11 (29% identical), and 9 more.